ANGPTL4 (angiopoietin like 4)
Diseases named in the same sentence as ANGPTL4 in open-access papers (continued):
Sharing a sentence is not in itself a finding about the gene and the disease.
hypertriglyceridemia (continued). "More recently, other studies carried out on humans and animal models suggested the involvement of ANGPTL4 in nephrotic syndrome, revealing that ANGPTL4 acts by linking proteinuria and hypertriglyceridemia through negative feedback loops." (PMID 28182091, 2017). "This gene, angiopoietin-like 4 (Angptl4), had just been cloned and identified as a PPAR target gene, and recombinant Angptl4 protein was shown to induce hypertriglyceridemia when injected into rodents." (PMID 24611049, 2014). "Since ANGPTL3, ANGPTL4, and ANGPTL8 are all LPL inhibitors, the absence of anyone of them would break the balance of triglyceride metabolism in turn would lead to hypotriglyceridemia or hypertriglyceridemia." (PMID 37170504, 2023).
colorectal cancer (37 papers, 2008 to 2025). A primary or metastatic malignant neoplasm that affects the colon or rectum. "In conclusion, our comprehensive proteogenomic and observational analyses suggest a protective role of lowering circulating ANGPTL4 concentrations in colorectal cancer risk." (PMID 40511612, 2025). "In analysis of 465 colon cancer patients, lower ANGPTL4 tumor expression was associated with reduced colorectal cancer-specific mortality risk (HRlog2 decrease = 0.66, 95% CI = 0.50 to 0.87, P = 2.92 × 10−3)." (PMID 40511612, 2025). "There was a high posterior probability that circulating ANGPTL4 concentrations and colorectal cancer risk shared a causal variant within the ANGPTL4 locus (PPcolocalization = 0.83)." (PMID 40511612, 2025). "Our integrative proteogenomic and observational analyses suggest a potential protective role of lower circulating ANGPTL4 concentrations in colorectal cancer risk." (PMID 40511612, 2025). "In combined drug-target Mendelian randomization and colocalization analyses of 78 473 cases and 107 143 controls, genetically proxied ANGPTL4 inhibition was associated with a reduced risk of colorectal cancer." (PMID 40511612, 2025). "In a model minimally adjusted for age and sex, we found evidence of a protective association of lower circulating ANGPTL4 concentrations with colorectal cancer risk (HR = 0.93, 95% CI = 0.86 to 0.99, P = .03)." (PMID 40511612, 2025). "We also found that lower colon tumor ANGPTL4 expression was associated with reduced risk of colorectal cancer-specific mortality (HR = 0.66, 95% CI = 0.50 to 0.87; P = 2.92 × 10−3)." (PMID 40511612, 2025). "Our findings leveraging genetic, observational, and molecular epidemiological designs recapitulate insights from preclinical studies indicating a protective effect of ANGPTL4 inhibition in colorectal cancer risk." (PMID 40511612, 2025). "And ERK pathway has been implicated in ANGPTL4-mediated colorectal cancer metastasis, angiogenesis as well as cell proliferation." (PMID 35860030, 2022). "Like EFNB2, ANGPTL4 has also been associated with the development of a range of cancers, including colorectal cancer, renal cell carcinoma, bladder tumours and gastric cancer." (PMID 19259415, 2008). "In analysis of 78 473 cases and 107 143 controls, there was evidence that genetically proxied circulating ANGPTL4 inhibition was associated with a reduced risk of colorectal cancer (odds ratio [OR] per SD decrease = 0.76, 95% confidence interval [CI] = 0.66 to 0.89, P = 5.52 × 10−4)." (PMID 40511612, 2025). "In analysis of 78 473 cases and 107 143 controls, genetically proxied circulating ANGPTL4 inhibition was associated with reduced colorectal cancer risk (ORSD decrease = 0.76, 95% confidence interval [CI] = 0.66 to 0.89, P = 5.52 × 10−4, PPcolocalization = 0.83)." (PMID 40511612, 2025). "Our findings thus validate and extend insights from preclinical models and can help to guide future work investigating mechanisms underpinning the effect of ANGPTL4 on colorectal cancer development." (PMID 40511612, 2025). "Through triangulation of evidence across proteogenomic, observational, and molecular epidemiological analyses, we prioritize ANGPTL4 as a potential therapeutic target for colorectal cancer prevention." (PMID 40511612, 2025). "For example, ANGPTL4 knockdown has been shown to inhibit proliferation, promote apoptosis, and suppress migration in colorectal cancer cell lines and to reduce colorectal tumor size in xenograft mouse models." (PMID 40511612, 2025). "Our findings potentially implicating ANGPTL4 in colorectal cancer development recapitulate insights from preclinical studies." (PMID 40511612, 2025). "As such, subsequent analyses were restricted to ANGPTL4 and colorectal cancer and its subsites only." (PMID 40511612, 2025).
colorectal cancer (continued). "Recently, high-throughput RNA sequencing of colorectal cancer cells cultured with Fusobacterium nucleatum showed that ANGPTL4, as one of the most significantly up-regulated genes, was increased upon infection." (PMID 39022746, 2024). "In both colorectal cancer and head and neck squamous cell carcinomas (HNSCCs), OA was found to enhance cancer metastasis via angiopoietin-like 4 (ANGPTL4) pathways." (PMID 37373069, 2023). "There is evidence that ANGPTL4 is ectopically expressed in certain malignant tumor tissues, including ovarian cancer, cervical cancer, colorectal cancer, pancreatic cancer and papillary thyroid cancer." (PMID 38159259, 2023). "Overexpression of ANGPTL4 promoted glucose uptake and glycolysis activity in colorectal cancer cells." (PMID 36147494, 2022). "Intriguingly, a clinical research study revealed that ANGPTL4 was significantly lower in the plasma of colorectal cancer patients than in their normal counterparts." (PMID 36553482, 2022). "By contrast, in melanoma, lung, and colorectal cancer, ANGPTL4 inhibits cell growth and angiogenesis." (PMID 31717924, 2019). "Our aim was to analyze the levels of ANGPTL-4 in colorectal cancer patients with a stable weight and those with cachexia in order to establish a relationship between ANGPTL-4 and the inflammatory process." (PMID 31741709, 2019). "Another study concerning the role of ANGPTL4 in colorectal cancer patients positively correlated ANGPTL4 expression and venous invasion, which is considered the first step of metastatic process." (PMID 28182091, 2017). "Increased Angptl4 expression has been shown in a variety of tumor tissues, such as oral Kaposi’s sarcoma, esophageal squamous cell carcinoma, gastric cancer, and colorectal cancer." (PMID 23617883, 2013). "Recently, prostaglandin E2 (PGE2) and hypoxia were shown to have a synergistic effect on the expression of ANGPTL4 in colorectal cancer." (PMID 22481923, 2012). "ANGPTL4 enhances colorectal carcinoma cell proliferation through its effects on STAT1 signaling mediated by the MAPK and Src signaling pathways." (PMID 22481923, 2012). "Moreover, adipose-derived stem cells (ADSCs) have been shown to elevate ANGPTL4 expression to mediate glycolysis in colorectal cancer cells." (PMID 40616161, 2025). "In addition, we found evidence that shared CAD and colorectal cancer signals in the ANGPTL4 gene with the same direction of effect were mediated via circulating ANGPTL4 concentrations." (PMID 40874306, 2025). "Similarly, in the colorectal cancer microenvironment, ANGPTL4 overexpression in endothelial cells activated JAK2/STAT3 signaling, enhancing angiogenesis and metastasis." (PMID 40616161, 2025). "Interestingly, prostaglandin E2, a putative key mediator of the effect of COX-2 on colorectal cancer, has also been reported to promote colorectal carcinoma cell proliferation via ANGPTL4 under hypoxic conditions." (PMID 40511612, 2025). "Dual targeting of TGF‐β signaling and ANGPTL4 may be a viable therapeutic strategy for peritoneal metastasis of colorectal cancer." (PMID 39286778, 2024). "Downregulated ANGPTL4 activates the ERK pathway thereby promoting colorectal cancer metastasis." (PMID 38311733, 2024). "However, in melanoma, lung, and colorectal cancer, the induction of ANGPTL4 is reported to inhibit cell growth, angiogenesis, and metastasis." (PMID 31717924, 2019). "As of now, this seems to be the first study suggesting that ANGPTL-4 may play an important role in the modulation of colorectal cancer cachexia." (PMID 31741709, 2019). "On the other hand, several studies showed that increased ANGPTL4 expression could inhibit tumor growth, metastasis, and angiogenesis in melanoma, lung, and colorectal cancers." (PMID 23925665, 2013). "Furthermore, clinical studies have correlated ANGPTL4 expression with venous and lymphatic invasion in human gastric and colorectal cancers, which further emphasized the role of ANGPTL4 in tumor metastasis." (PMID 23925665, 2013).
colorectal cancer (continued). "Furthermore, clinical studies have correlated ANGPTL4 expression to venous and lymphatic invasion in human gastric and colorectal carcinoma, which further emphasizes the role of ANGPTL4 in tumor metastasis." (PMID 22481923, 2012). "However, colorectal cancer (CRC) studies have identified opposite roles of ANGPTL4." (PMID 36447119, 2023). "Previous studies confirmed that ANGPTL4 was significantly associated with vein invasion and tumor invasion depth in human colorectal cancer, and all patients with distant metastases presented immunopositive for ANGPTL4, suggesting that ANGPTL4 could promote distant metastasis." (PMID 36793937, 2023). "In addition, it was demonstrated that HCPT116 colorectal cancer cells overexpressing ANGPTL-4 have a lower rate of apoptosis due to a decrease in the mRNA and protein levels of Bax (a pro-apoptotic protein) and an increase in Bcl-xl levels (inhibitor of apoptosis)." (PMID 31741709, 2019). "We observed increased levels of numerous pro‐angiogenic proteins, including VEGF, PXDN, ANGPTL4 and TIMP‐1, a factor upregulated in colorectal cancer EVs that induces ECM remodelling in recipient fibroblasts." (PMID 41179923, 2025). "The clinical relevance of these results is further validated by the findings that the expressions of both ANGPTL4 and STAT1 are elevated in half of the human colorectal cancers tested." (PMID 22481923, 2012). "Moreover, tumor‐infiltrating adipose stem cells promoted glycolysis and anoikis resistance in colorectal cancer cells, and ultimately resulted in peritoneal metastasis through the TGF‐β1/SMAD3/ANGPTL4 axis." (PMID 39286778, 2024).
coronary artery disease (37 papers, 2011 to 2025). "This is supported by human genetic evidence that loss-of-function variants in ANGPTL4 are associated with lower plasma triglycerides and reduced coronary artery disease risk." (PMID 40511612, 2025). "Genetic study has reported an association between variants of Angptl4 and a reduced risk of coronary heart disease." (PMID 39014511, 2024). "Another study showed the relationship between mutations inactivating the ANGPTL4 gene on the risk of ischemic heart disease." (PMID 36614969, 2022). "Angptl4 was recently shown to be associated with a variety of diseases, such as diabetes, pancreatitis, coronary artery disease (CAD), and some musculoskeletal diseases including disc degeneration, rheumatoid arthritis, and osteoporosis." (PMID 36071864, 2022). "Genetic variations in apolipoprotein C-III ( APOC3) and angiopoietin-like 4 (ANGPTL4) have been associated with risk for coronary artery disease (CAD)." (PMID 33171725, 2020). "The p.E40K mutation in ANGPTL4 also associates with reduced risk of coronary disease (Stitziel and Myocardial Infarction Genetics and CARDIoGRAM Exome Consortia Investigators, 2016)." (PMID 31024910, 2019). "Some studies have also showed that ANGPTL4 loss-of-function mutations are associated with substantially lower TG levels, and a lower risk of coronary artery disease (CAD) and type 2 diabetes (T2D)." (PMID 30323852, 2018). "For example, ANGPTL4 is associated with metabolism of lipoproteins, and is a risk factor for coronary disease." (PMID 28837672, 2017). "Patients with this ANGPTL4 mutation showed a 19% lower risk of coronary heart disease." (PMID 36614969, 2022). "Although decreased lipid content is generally atheroprotective, E40K, a loss of function variant of ANGPTL4, was associated with increased coronary heart disease risk despite being associated with an atheroprotective lipid profile, suggesting that ANGPTL4 influences parameters beyond lipid levels." (PMID 27460411, 2016). "Additional evidence for their physiological importance are provided by genome-wide association studies (GWAS), which showed that a polymorphic variant of ANGPTL4, E40K (E15K in the mature protein) is associated with mild hypotriglyceridemia and reduced risk of coronary artery disease." (PMID 27929370, 2016). "E40K carrier status was found to be associated with a significantly reduced risk of coronary artery disease, suggesting that the inactivation of ANGPTL4 may be a viable pharmacological strategy to improve plasma lipid levels and reduce the risk of coronary artery disease." (PMID 34801488, 2021). "Individuals carrying the pE40K variant of ANGPTL4 have lower triglyceride levels, higher high-density lipoprotein (HDL) cholesterol, and a reduced risk of coronary artery disease." (PMID 40652248, 2025). "In animal models, ANGPTL4 has shown utility in preserving vascular integrity and reducing infarct size in ischemic heart disease and in modulating vascular permeability in diabetic macular edema." (PMID 40006981, 2025). "SNPs in LPL and posttranscriptional regulators of LPL including ANGPTL4, APOA5, APOC3, and ANGPTL3 that modulate plasma TAGs have been persuasively linked to coronary artery disease (CAD)." (PMID 29563332, 2018). "Genetic studies have revealed that a polymorphic variant in ANGPTL4 (ANGPTL4E15K, with a ~3% prevalence in Caucasians) is associated with lower plasma triglyceride levels and reduced risk of coronary artery disease." (PMID 27929370, 2016). "Although they are all associated with metabolic disorders, it seems that only in subjects with LP, ANGPTL4 could serve as a marker of metabolic complications, especially coronary artery disease." (PMID 36144281, 2022). "At the genetic level, loss-of-function mutations in ANGPTL4 are associated with lower plasma triglycerides and higher plasma HDL-C levels, and a reduced risk of coronary artery disease, suggesting that ANGPTL4 is a viable pharmacological target for reducing cardiovascular risk." (PMID 34801488, 2021).
coronary artery disease (continued). "For example, carriers of loss-of-function mutations in ANGPTL4 had 35 % lower TG concentrations than non-carriers; these mutations were also associated with protection from coronary artery disease." (PMID 27551321, 2016). "ANGPTL4 belongs to the ANGPTL superfamily and can regulate lipid metabolism, leading to coronary heart disease and many other cardiovascular diseases." (PMID 36467503, 2022). "We conclude that therapies specifically aimed at decreasing plasma ANGPTL3, ANGPTL4, and APOC3 levels are expected to reduce the risk of coronary artery disease without raising safety concerns." (PMID 38895109, 2024). "Angiopoietin-like 4 (ANGPTL4) is a member of angiopoietin-like proteins, which play an important role in lipid metabolism, and its serum concentration has been proposed as a biomarker of cardiometabolic complications, especially coronary artery disease (CAD)." (PMID 36144281, 2022). "Lipid metabolism related factors, such as angiopoietin‐like protein 3 (ANGPTL3), angiopoietin‐like 4 (ANGPTL4), fatty acid‐binding protein 4 (FABP4) are newly discovered factors that can affect coronary artery disease (CAD)." (PMID 38425231, 2024).
melanoma (31 papers, 2010 to 2025). A malignant, usually aggressive tumor composed of atypical, neoplastic melanocytes. "ANGPTL4 expression was associated with increased hypoxia in Melanoma, and increased hypoxia and metastasis in BRCA." (PMID 40233044, 2025). "As ANGPTL4 reprograms endothelial permeability we asked if melanoma-associated ANGPTL4 regulates either directly or indirectly the integrity of TJs in BEC." (PMID 29100268, 2017). "Taken together these findings indicate that ANGPTL4 promotes the malignancy phenotype of primary melanomas of risk to metastasize to the brain." (PMID 29100268, 2017). "A significant higher expression of ANGPTL4 was observed in the brain macro-metastatic variants of these melanomas than in the corresponding cutaneous variants (P < 0.05)." (PMID 29100268, 2017). "In a previous study we showed that MBM variants of 3 different human melanoma xenograft models express higher levels of ANGPTL4 than their corresponding cutaneous variants." (PMID 29100268, 2017). "Recently, the use of a monoclonal antibody against ANGPTL4 caused a significant retardation in the growth of melanoma in a murine model via a redox-based apoptotic pathway." (PMID 22481923, 2012). "It has been reported that ANGPTL4 plays a role in epithelial-to-mesenchymal transition (EMT) in melanoma and ovarian cancer by regulating the ERK1/2 signaling pathways." (PMID 40233044, 2025). "Alternatively, expression of ANGPTL4 was shown to be regulated by hypoxia in tumor cells, and ANGPTL4 is highly expressed in melanoma brain metastasis, suggesting that ANGPTL4 is involved in melanoma metastasis." (PMID 39940783, 2025). "High expression of ANGPTL4 predicts adverse clinical outcomes in tumors, such as renal clear cell carcinoma, cholangiocarcinoma, melanoma, bladder cancer, and oral cancer." (PMID 36447119, 2023). "ANGPTL4 expression was found upregulated in breast tumors, basal cell carcinoma, melanoma, as well as CRC cells, and cancer cell lines derived from breast, lung, and liver cancers." (PMID 34331381, 2021). "In contrast, some studies have found no precise function for ANGPTL4 in cancer progression or even some of them discovered that the elevated expression of ANGPTL4 prevents tumor growth, invasion, and angiogenesis in melanoma and colorectal cancers." (PMID 33602983, 2021). "This suggested that reduced level of phospho-ERK in drug-selected melanoma cells was mediated by higher expression of ANGPTL4, which is consistent with previous observation." (PMID 33196458, 2020). "We also examined the expression of melanoma stem-cell markers after suppression of ANGPTL4 expression." (PMID 33196458, 2020). "It has also been shown that increased ANGPTL4 expression inhibits melanoma and colorectal tumour growth, metastasis, and angiogenesis." (PMID 31963541, 2020). "Microarray and bioinformatics analysis highlighted the high expression of angiopoietin-like 4 protein in drug-selected melanoma stem-like cells." (PMID 33196458, 2020). "Our finding would be applicable to explore the mechanism of melanoma stemness and use angiopoietin-like 4 as potential biomarkers to identify melanoma stem-like cells." (PMID 33196458, 2020). "In summary, we suggested the higher ANGPTL4 expression in drug-selected melanoma cell subpopulation account for melanoma-stemness features of in vitro tube formation ability, sphere formation, drug-resistance, and reduced ERK phosphorylation." (PMID 33196458, 2020). "While high ANGPTL4 expression is correlated with poor prognosis in oral cancer, it seems to inhibit melanoma and lung cancer tumor growth, metastasis and angiogenesis." (PMID 29389861, 2018). "The expression of ANGPTL4 was measured in a cohort of 12 melanoma patients with paired primary melanoma (PRM), melanoma lymph node metastasis (LNM), and MBM." (PMID 29100268, 2017). "This indicates the ANGPTL4 expression effect is context dependent on the source of the melanoma cell." (PMID 29100268, 2017).